ENSG00000276664
Gene: Miscellaneous RNA gene on chromosome 22 (30,971,005 to 30,971,149, forward strand). Ensembl gene ENSG00000276664.
Gene Ontology:
Biological process: regulation of eye photoreceptor cell development